IFNA2 (interferon alpha 2)
Description:
Produced by macrophages, IFN-alpha have antiviral activities.
Synonyms: IFN-alpha-2; LeIF A; IFNA2B; IFNA; IFN-alphaA
Tractability: Small molecule: it has a high-quality binding pocket. Antibody: a drug acting on it is in phase 2 or 3 trials; UniProt places it where antibodies can reach, with high confidence; its Gene Ontology location is reachable by antibodies, with high confidence; UniProt predicts a signal peptide or a membrane-spanning region.
Target class: Secreted protein
Gene: Protein-coding gene on chromosome 9 (21,384,255 to 21,385,398, reverse strand). Ensembl gene ENSG00000188379.
Subcellular location: Secreted
Pathways (Reactome):
Immune System: Interferon alpha/beta signaling; Regulation of IFNA/IFNB signaling; TRAF6 mediated IRF7 activation
Disease: Evasion by RSV of host interferon responses; SARS-CoV-2 activates/modulates innate and adaptive immune responses
Hemostasis: Factors involved in megakaryocyte development and platelet production
Gene Ontology:
Molecular function: cytokine activity; protein binding; type I interferon receptor binding; cytokine receptor binding
Biological process: cell surface receptor signaling pathway via STAT; defense response to virus; host-mediated suppression of symbiont invasion; negative regulation of DNA-templated transcription; negative regulation of gene expression; negative regulation of interleukin-13 production; negative regulation of interleukin-5 production; negative regulation of T cell differentiation; negative regulation of T-helper 2 cell cytokine production; type I interferon-mediated signaling pathway; adaptive immune response; apoptotic process; B cell activation involved in immune response; cell surface receptor signaling pathway; cell-cell signaling; cellular response to virus; humoral immune response; inflammatory response; natural killer cell activation involved in immune response; response to exogenous dsRNA; T cell activation involved in immune response; defense response
Cellular component: extracellular matrix; extracellular region
Genetic constraint (gnomAD): Loss-of-function variants: 1 observed, 0.56 expected, observed/expected ratio (o/e) 1.78, 90% interval 0.33 to 1.92. That is too few expected variants to judge how well the gene tolerates losing a copy. Missense variants: 260 observed, 217.57 expected, observed/expected ratio (o/e) 1.2, 90% interval 1.08 to 1.32. Synonymous variants: 91 observed, 84.58 expected, observed/expected ratio (o/e) 1.08, 90% interval 0.91 to 1.28.
Homologues: Orthologues: chimpanzee IFNA2 (89% identical), pig IFN-ALPHA-9 (69% identical), pig IFN-ALPHA-8 (68% identical), pig IFN-ALPHA-15 (68% identical), pig IFN-ALPHA-13 (67% identical), pig IFNA1 (67% identical), pig IFN-ALPHA-4 (66% identical), pig IFN-ALPHA-17 (65% identical), pig IFN-ALPHA-1 (64% identical), pig IFN-ALPHA-10 (64% identical), rabbit IF1AD2 (64% identical), rabbit IF1AD7 (64% identical), and 31 more. Paralogues in human: IFNA6 (86% identical), IFNA5 (84% identical), IFNA13 (83% identical), IFNA1 (82% identical), IFNA14 (82% identical), IFNA8 (82% identical), IFNA21 (82% identical), IFNA4 (82% identical), IFNA16 (81% identical), IFNA10 (81% identical), IFNA17 (81% identical), IFNA7 (78% identical), and 4 more.
Diseases named in the same sentence as IFNA2 in open-access papers:
IFNA2 is named in the same sentence as 198 diseases in open-access papers, as found by Europe PMC text mining. Sharing a sentence is not in itself a finding about the gene and the disease. The quoted sentences say what the papers report.
COVID-19 (97 papers, 2020 to 2025). A disease caused by infection with severe acute respiratory syndrome coronavirus 2. "Our data have revealed dissociation between increased blood IFN-α2a levels and enhanced type I IFN–associated transcriptional scores in whole blood and low IFNA2 transcriptional levels in whole blood from patients with COVID-19." (PMID 33232303, 2021). "In the severe COVID-19 group, levels of autoantibodies against IL-1α, IFNα2, TNFα, osteopontin and IFNβ all showed high correlation." (PMID 38491326, 2024). "For the IgG autoantibodies, the severe COVID-19 group trended for higher levels in many of the analytes tested and had statistically significant higher levels of both IL-3 and IFNα2 cytokines (p ≤ 0.05; Wilcoxon–Mann–Whitney)." (PMID 38491326, 2024). "In the individuals with severe COVID-19, we found that the autoantibody levels of IL-1α, IFNα2, TNFα, osteopontin, and IFNβ showed a high correlation with each other." (PMID 38491326, 2024). "This study identified 30 nodes associated with cytokine storm, ARDS, and inflammatory process of COVID-19, namely, IL-6, IL-6R, NF-κB, IL-2, IL-2RA, IFNA2, IFNAR1, COX5A, and COX411." (PMID 39640429, 2024). "It is worth noting that the three autoAb-positive patients hospitalized with COVID-19 in 2020 (P18, P28, and P32) first developed neutralizing anti-IFNα2 autoAbs in 2008, 2013, and 2014 (i.e., 6–12 years prior to the start of the pandemic)." (PMID 39017930, 2024). "Type 1 IFNs, specifically IFNA2, whose levels are increased in patients with severe COVID-19, increase ACE2 expression and viral copy number in vitro." (PMID 38074511, 2024). "A single subcutaneous injection of Peg-IFNα2 was administered to a 25-year-old woman with known TLR3 deficiency [p.(Pro455Ser)] and COVID-19 who had two episodes of herpes simplex encephalitis in childhood, but had no further serious viral infections." (PMID 37175768, 2023). "A total of 13/124 measures including CCL5, CCL17, IL-18, IFNα2, Fractalkine, classical monocytes, T cells, and CD4Temra exhibited significant sex differences in female vs. male COVID-19 patients." (PMID 37998327, 2023). "Anti-IFNα2 autoantibodies were largely confined to the IgG class, as few individuals had IgA or IgM reactivity to IFNα2, although 1 male COVID-19 patient (2 samples) was highly positive for anti-IFNα2 IgM." (PMID 35788562, 2022). "Due to its known antiviral activity and its clinical administration in chronic viral infections, IFN-I, specifically IFNα2 or IFNβ, were already used in a variety of different clinical trials in patients with mild or severe COVID-19." (PMID 35131898, 2022). "Although both subtypes are significantly up-regulated in the plasma of COVID-19 patients, only IFNA2 levels correlate with the IFN-α scores and with mRNA expression of well recognized IFN-inducible genes (ISGs), such as ISG15 and OAS2." (PMID 35217532, 2022). "When such assays are applied to COVID-19 patient samples, more consistent results were observed, with severe patients overall showing lower levels of circulating IFNα2,15,28–31." (PMID 36434007, 2022). "There are still some debates about the therapeutic efficacy of different IFN-α therapies, although a phase 2 open-label, randomized clinical trial with moderate COVID-19 patients was used to evaluate the efficiency of pegylated interferon-alpha-2b (IFN-α-2b)." (PMID 36362912, 2022). "Consistent with a more active type I interferon system in women, higher levels of IFNα2 were detected in female COVID-19 patients than in male patients in the same cohort." (PMID 36077273, 2022). "We therefore used our antibody-binding assay to assess anti-IFNα2 and anti-IFNω IgG, IgA, and IgM autoantibodies in tracheobronchial secretions (TBSs) obtained from 88 of the severe COVID-19 patients in our cohort." (PMID 35788562, 2022). "A recent report has also noted either stable or fluctuating levels of anti-IFNα2 IgG autoantibodies following hospital admission for COVID-19." (PMID 35788562, 2022).
COVID-19 (continued). "In male participants, EGF, GM-CSF, IL-1ra, IL-1α, IL-1β, IL-2, IL-4, IL-7, IL-15, EOTAXIN, MDC, MIP-1α, MIP-1β, IFNα2, and sCD40L were significantly lower in COVID-19 patients compared to controls." (PMID 36554094, 2022). "For 9 of the 12 severe COVID-19 patients who were positive for anti-IFNα2 IgG autoantibodies, we had multiple plasma samples that were collected around the time of ICU admission, ICU discharge, or at hospital discharge." (PMID 35788562, 2022). "In this independent cohort, we again observed a strongly reduced IFNα2 and IFNβ secreted response to Poly:IC, LPS and R848 stimulation in critical COVID-19 patients in comparison to healthy controls." (PMID 36434007, 2022). "In this study, we report the presence of IgG autoantibodies that bind and neutralize the type I IFNs, IFNα2 and IFNω, in plasmas/sera and TBSs from approximately 10% of critically ill COVID-19 patients admitted to a tertiary ICU in Switzerland." (PMID 35788562, 2022). "Serum levels of EGF, G-CSF, GM-CSF, IL-1ra, IL-1α, IL-1β, IL-2, IL-4, IL-7, IL-8, EOTAXIN, fractalkine, GRO, P-10, MDC, MIP-1α, MIP-1β, IFNα2, and sCD40L were significantly lower in female COVID-19 patients compared to controls." (PMID 36554094, 2022). "We present a dynamic description of immuno-inflammatory derangements in 64 critically ill COVID-19 patients including plasma IFNα2 levels and IFN-stimulated genes (ISG) score measurements." (PMID 33845874, 2021). "This exercise revealed that, whereas the DS IFN score tracks preferentially with IFNG and IFNL1 in DS, this same ISG signature correlates significantly with eight different IFNs in COVID-19, five of which are type I IFNs (i.e., IFNA2, IFNA7/17/21, IFNA1, IFNA4/16, and IFNA10)." (PMID 37379383, 2023). "In addition, normalized IFNA2 transcripts only weakly correlated with the 28-gene type I IFN score in COVID-19 patients (Spearman’s = 0.07; P = 0.55), in contrast to their significant correlation in patients with monogenic IFNopathies (Spearman’s P = 0.57; P = 0.0015)." (PMID 33232303, 2021). "While the literature surrounding this is sparse, one study included in this meta-analysis concluded that early administration of interferon-alpha-2b could induce positive outcomes in COVID-19 patients compared to standard treatment, while its late administration was associated with slower recovery." (PMID 32869016, 2020). "Serum levels of the type I interferon cytokines (IFNα2 and IFNβ) and the type II interferon cytokine IFN-γ also increased with more severe COVID-19." (PMID 37935729, 2023). "One study conducted at Union Hospital in Wuhan, China, assessed the effectiveness of interferon-alpha-2b (IFN-a2b) and arbidol on moderate cases of COVID-19 patients with viral pneumonia." (PMID 34452063, 2021). "Assessment of anti-IFNβ autoantibody levels did not reveal differences between severe COVID-19 patients who were positive or negative for anti-IFNα2 IgG, either in plasma or TBS samples." (PMID 35788562, 2022). "Both IFNA2 and IFNA6 are significantly up-regulated in the COVID-19+ cohort." (PMID 35217532, 2022). "The low transcriptional levels of IFNA2 detected in blood are consistent with decreased numbers of circulating plasmacytoid DCs (pDCs) and impaired production of type I IFN by circulating pDCs in COVID-19 patients reported by others." (PMID 33232303, 2021). "To investigate this particular aspect of COVID-19 immune response, we monitored selected immunological parameters, including IFNα2 measurement and IFN-stimulated genes (ISG) transcriptomic signature, in a group of 64 COVID-19 patients requiring ICU care over a 3-week period after ICU admission." (PMID 33845874, 2021). "We observed that 11.3% of male severe COVID-19 patients (9/80 individuals, 15 samples) and 13.0% of female severe COVID-19 patients (3/23 individuals, 8 samples) had clearly detectable IgG autoantibodies targeting IFNα2 in their plasma, which were not present in the plasma of 130 healthy donors." (PMID 35788562, 2022).
viral infection (44 papers, 2008 to 2025). "Accordingly, virus infection causes higher expression of IFNa2, IFNb1, OAS1, and STAT2 in Nlrx1−/− mice when compared to wild-type mice." (PMID 33525590, 2021). "By contrast, universal IFNα2 or bat IFNλ1-like-treatment or virus-infection of bat nasalORG (MARV), alvORG (MARV, MERS, SeV) or SIORG (SeV), resulted in minimal or no changes in the expression of these pro-inflammatory genes." (PMID 40399606, 2025). "IFNα2 and Tα1 are used effectively for the treatment of viral infections and different types of cancers." (PMID 34203928, 2021). "Human interferon α2 (IFNα2) and thymosin α1 (Tα1) are therapeutic proteins used for the treatment of viral infections and different types of cancer." (PMID 34203928, 2021). "Interferon-alpha 2 (IFNα2) is a type of biopharmaceutical which is equally effective for the treatment of viral infections and different types of cancers." (PMID 34203928, 2021). "In the super-SILAC detected DEPs, consistent prediction of IFNG was computed out; in addition, other known viral infection relevant pathways, such as IFNA2, IFNB1 and TLR, were also deemed up-stream activators by IPA." (PMID 28117408, 2017). "Another protein examined in this study, IFNα2 is used for the treatment of viral infection and cancer." (PMID 27195765, 2016). "IFNα2 belongs to a family of proteins produced by leukocytes that are primarily involved in innate immunity, particularly in response against viral infection." (PMID 26035055, 2015). "IFNα2 belongs to the large family of interferon alpha, which is Th1 cytokine in response primarily to viral infection." (PMID 24473087, 2014). "IFNα-2 is the most well-known IFNα subtype that is also used as a treatment for viral infections." (PMID 36423126, 2022). "The requirement for Mavs, a component of the cytoplasmic viral RNA sensing pathway, in monocytes for the induction of IFNα2 mRNA in response to RRV infection suggested that direct viral infection of monocytes may be necessary for the induction of type I IFN." (PMID 29244871, 2017). "IFNβ, IFNα4, and IFNα2 transcripts could be detected as early as 4 h after virus infection." (PMID 22291574, 2012). "Interferon-alpha 2b (IFN-α 2b) is a therapeutic protein used for the treatment of cancer, viral infections, and auto-immune diseases." (PMID 35683707, 2022). "Using IPA to examine the genes showing DE mediated by ART in HIV+ cells, we found that ART may decrease viral infection/replication by inhibiting E2F, E2F1, and IFNA2 and by activating let-7, representing upstream regulators." (PMID 32723919, 2020). "In NHP MDM the response to 17D virus infection was similar to what was seen in human MDM with evident increases in IFNα2 and TNFα, but little evidence of a pro-inflammatory response." (PMID 27191161, 2016).
melanoma (40 papers, 1990 to 2026). A malignant, usually aggressive tumor composed of atypical, neoplastic melanocytes. "Four prospective trials in Atkins’ observation study showed that in patients with high-risk resection of melanoma, adjuvant therapy with high-dose interferon-alpha-2b can effectively improve the relapse-free survival rate but not the overall survival rate." (PMID 34675134, 2021). "Thus, both the individual trials and this meta-analysis provide evidence that adjuvant IFNα2 significantly reduces the risk of relapse and mortality of high-risk melanoma, albeit with a relatively small absolute improvement in survival in the overall population." (PMID 18954464, 2008). "Since the approval of IFNα2 for use against advanced melanoma over 30 years ago, the therapeutic potential of other subtypes has been largely understudied." (PMID 34552594, 2021). "Bevacizumab combined with interferon-alpha 2A and interferon-alpha 2B for metastatic melanoma has been investigated and showed clinical response in 24% of patients with stage IV melanoma." (PMID 33562829, 2021). "This was systematically evaluated by transplantation of B16 murine melanoma cells secreting five unique IFNα subtypes (B16_IFNα2; B16_IFNα4; B16_IFNα5; B16_IFNα6; B16_IFNα9) into a pre-clinical murine model." (PMID 32308653, 2020). "Postoperative adjuvant immunotherapy using interferon alpha-2b has been used to prevent relapse and has been approved by the United States Food and Drug Administration for the treatment of metastasized melanoma." (PMID 32341830, 2020). "B16 melanoma cells were engineered to overexpress IFNα2, α4, α5, α6, or α9, but only IFNα2- and α9-expressing tumors were effectively controlled in an adaptive-immunity dependent manner." (PMID 33408718, 2020). "Exogenous treatment with both IFNα2 and IFNβ1 exerted antitumour and anti-metastatic effects, particularly to lymph nodes, in human melanoma xenografts." (PMID 31342168, 2019). "Pegylated interferon alpha-2b, vemurafenib and ipilimumab were approved for treatment of melanoma by Food and Drug Administration in the past year." (PMID 22333219, 2012). "All but 6 patients had received prior systemic therapy for melanoma, and 27 (75%) had previously received the cytokines IFNα2 or interleukin-2 (IL2) alone or in combination with chemotherapy." (PMID 20109236, 2010). "High-dose interferon-alpha 2b (IFN-α 2b) is the only approved systemic therapy in the United States for the adjuvant treatment of melanoma." (PMID 20712892, 2010). "In melanoma patients treated with adenovirus-transduced DC and high-dose systemic interferon-alpha-2b (IFN-α2b), a detailed phenotypic and functional analysis of blood NK cells was carried out by mFC, multiplex gene expression analysis and serum content analysis." (PMID 33193392, 2020). "IFNα2 is used to treat patients with several malignant diseases such as hairy cell leukemia, lymphoma, renal cell carcinoma, bladder cancer, breast cancer, and melanoma (Borden 1984, Kirkwood 2002)." (PMID 23913484, 2013). "Serial thyroid functions studies were carried out in patients with melanoma and renal cell carcinoma treated with interleukin-2 (3 MU m-2 by continuous infusion days 1-4) and interferon alpha-2a (6 MU m-2 subcutaneously on days 1 and 4), both given on alternate weeks." (PMID 2390468, 1990). "We herein compare topical interferon alpha 2b (IFN-α2b) to topical mitomycin C (MMC) in the adjuvant management after excision of primary acquired melanosis with atypia (PAM) and melanoma of the conjunctiva/cornea (CM)." (PMID 36255550, 2023). "Human interferon alpha 2b (IFN-α2b) was approved for the treatment of hairy cell leukemia in 1986 and recombinant IL-2 for treating melanoma and renal cancers in 1992." (PMID 37509400, 2023).
melanoma (continued). "More than 10 different drug types have been approved by the FDA for the treatment of melanoma, including dacarbazine chemotherapy, BRAF and MEK-targeted therapy, recombinant interferon alpha-2b and IL-2, immune checkpoint inhibitors (ICIs), and oncolytic viral therapy (T-VEC)." (PMID 35495634, 2022). "Interferon-alpha 2 is a cytokine that promotes antigen presentation via upregulation of MHC-I/II, leading to increased infiltrations of dendritic cells and T cells into melanoma tumors." (PMID 35205315, 2022).
lupus (12 papers, 2013 to 2025). "The importance of interferons was highlighted in our previous results on the TLR4 signaling pathway, where TLR4, TICAM1, TICAM2, TBK1, IRF3, IFNA1, and IFNA2 mRNAs showed changes in the murine lupus-like models." (PMID 29349090, 2017). "IPA also indicated the type-I interferon IFNA2 (interferon alpha 2) as a common upstream regulator, so we suspect that type-I interferon pathways are the targets of the epigenetic changes in lupus." (PMID 23950730, 2013).